MMP1 (matrix metallopeptidase 1)
Description:
Cleaves collagens of types I, II, and III at one site in the helical domain. Also cleaves collagens of types VII and X. In case of HIV infection, interacts and cleaves the secreted viral Tat protein, leading to a decrease in neuronal Tat's mediated neurotoxicity.
Synonyms: CLG
Tractability: Small molecule: an approved drug acts on it; a structure with a bound ligand is known; a high-quality ligand is known; it has a binding pocket of medium quality; it belongs to a druggable protein family. Antibody: UniProt places it where antibodies can reach, with high confidence; its Gene Ontology location is reachable by antibodies, with high confidence; UniProt predicts a signal peptide or a membrane-spanning region. PROTAC: ubiquitination databases record sites on it; a small molecule that binds it is known.
Target class: Metallo protease; Metallo protease M10A subfamily; Metallo protease MAM clan; Protease; Enzyme
Chemical probes: CHEMBL526566
Gene: Protein-coding gene on chromosome 11 (102,789,401 to 102,798,160, reverse strand). Ensembl gene ENSG00000196611.
Subcellular location: Secreted, extracellular space, extracellular matrix
Subcellular location (Human Protein Atlas): Vesicles; Predicted to be secreted
Pathways (Reactome):
Extracellular matrix organization: Activation of Matrix Metalloproteinases; Collagen degradation; Degradation of the extracellular matrix
Hemostasis: Basigin interactions
Immune System: Interleukin-4 and Interleukin-13 signaling
Metabolism of proteins: Regulation of Insulin-like Growth Factor (IGF) transport and uptake by Insulin-like Growth Factor Binding Proteins (IGFBPs)
Gene Ontology:
Molecular function: endopeptidase activity; metalloendopeptidase activity; peptidase activity; serine-type endopeptidase activity; zinc ion binding; metallopeptidase activity
Biological process: cellular response to UV-A; positive regulation of protein-containing complex assembly; proteolysis; collagen catabolic process; extracellular matrix disassembly; extracellular matrix organization
Cellular component: extracellular region; extracellular matrix
Genetic constraint (gnomAD): Loss-of-function variants: 44 observed, 43.81 expected, observed/expected ratio (o/e) 1, 90% interval 0.79 to 1.29. The upper end of that interval is the gene's LOEUF score, 1.29, which puts it in group 5 of 6, group 1 being the genes least tolerant of losing a copy. Missense variants: 580 observed, 553.25 expected, observed/expected ratio (o/e) 1.05, 90% interval 0.98 to 1.12. Synonymous variants: 220 observed, 195.21 expected, observed/expected ratio (o/e) 1.13, 90% interval 1.01 to 1.26.
Homologues: Orthologues: chimpanzee MMP1 (99% identical), macaque MMP1 (97% identical), rabbit MMP1 (86% identical), pig MMP1 (85% identical), dog MMP1 (81% identical), guinea pig MMP1 (60% identical), mouse Mmp1a (59% identical), rat Mmp1 (57% identical), mouse Mmp1b (57% identical), rat Mmp1b (56% identical), tropical clawed frog mmp1 (54% identical), Caenorhabditis elegans zmp-3 (28% identical), and 4 more. Paralogues in human: MMP8 (57% identical), MMP3 (54% identical), MMP10 (52% identical), MMP27 (49% identical), MMP12 (48% identical), MMP13 (47% identical), MMP20 (43% identical), MMP2 (42% identical), MMP24 (40% identical), MMP16 (40% identical), MMP14 (39% identical), MMP15 (39% identical), and 11 more.
Diseases named in the same sentence as MMP1 in open-access papers:
MMP1 is named in the same sentence as 531 diseases in open-access papers, as found by Europe PMC text mining. Sharing a sentence is not in itself a finding about the gene and the disease. The quoted sentences say what the papers report.
breast carcinoma (283 papers, 1999 to 2026). "Overexpression of MMP-1 is linked to poor prognoses in lung cancer, breast cancer, and various other malignancies." (PMID 39976778, 2025). "In a recent investigation addressing tamoxifen resistance in breast cancer, elevated expression of MMP1 was identified as a resistance‐driving gene associated with promoter methylation." (PMID 38639039, 2024). "Previous studies have reported that expression of MMP-1 is associated with invasive behavior in breast cancer." (PMID 38321552, 2024). "Myofibroblasts are important sources of MMPs in breast cancer, and tumour progression and adverse reactions are associated with strong expression of MMP-1, MMP-7, and MMP-9, as well as fibroblast-specific production of MMP-9, MMP-11, and MMP-1431." (PMID 38956273, 2024). "The results showed that loss of miR-202–3p in breast cancer cells enhances their transmigration across the brain endothelium through upregulation of MMP-1." (PMID 38577014, 2024). "MMP1 overexpression has been linked to the BM of breast cancer, with MMP1 being upregulated in brain metastatic breast cancer cells compared to their parental cell lines." (PMID 37190188, 2023). "The invasiveness of breast cancer is tightly linked to MMP1, and high expression of MMP1 usually predicts a poor prognosis in breast cancer." (PMID 36900408, 2023). "Increased MMP-1 expression has been observed in oral, bladder, gastric, and breast cancers and was linked to a poor prognosis for these diseases." (PMID 37513440, 2023). "It is notable that serum levels of some MMPs, such as MMP-1, -2, and -9, are associated with prognosis in breast cancer." (PMID 36741729, 2022). "Overexpression of MMP-1 contributes to invasion and metastasis in breast cancer, and it potentially serves as a diagnostic marker and target for breast cancer." (PMID 34980125, 2022). "Methylation was found to be inversely associated with MMP1 expression level in breast cancer tissues, and patients with lower MMP1 expression exhibited a better prognosis for survival." (PMID 35267540, 2022). "The high expression of MMP1 in breast cancer tissues made it promising as one of the diagnostic markers of BRCA." (PMID 35069702, 2021). "Elevated levels of MMP-1 have been detected in breast cancer and are reported to be associated with breast cancer progression and poor prognosis." (PMID 34771423, 2021). "We next investigated the effect of miR-202-3p loss on the expression of MMP-1 in breast cancer cells." (PMID 33002044, 2020). "Down regulation of MMP-1,−2,−3,−9,−10, and−13 was associated with cancer progression and poor prognosis in breast cancer patients." (PMID 33042020, 2020). "In line with this, MMP1 expression in immune cells at the sentinel lymph nodes was associated with sequential metastasis across lymph nodes in breast cancer." (PMID 33396463, 2020). "On the other hand, the mean serum MMP-1 level was found to be decreased in the breast cancer group, in an inverse association with tumor size." (PMID 32425999, 2020). "Loss of miR-202-3p in breast cancer cells enhanced their transmigration through the brain endothelium by upregulating MMP-1 and disrupting the inter-endothelial junctions (claudin-5, ZO-1 and ß-catenin)." (PMID 33002044, 2020). "The overexpression of MMP1 is strongly associated with unfavorable prognosis in multiple malignancies including breast cancer, oesophageal squamous cell carcinoma, and ovarian cancer." (PMID 33381538, 2020). "Collectively, these data demonstrate that loss of miR-202-3p expression causes a significant increase in MMP-1 expression in breast cancer cells with low brain propensity." (PMID 33002044, 2020). "We showed evidence of reduced levels of miR-202-3p in brain metastatic breast cancer cells, and that loss of miR-202-3p induces MMP-1 expression, disrupts the brain endothelium integrity and promotes transmigration of BC cells." (PMID 33002044, 2020).
breast carcinoma (continued). "Silencing Cyr61 in invasive breast cancer cells caused a major loss of MMP-1 induction from stromal fibroblasts and inhibited the tumorigenicity of breast cancer cells." (PMID 31824306, 2019). "High expression of MMP1 has also been associated with the development of metastasis in colorectal and breast cancer." (PMID 29120535, 2018). "MMP1 was also shown to cause migration by binding to PAR1 in breast cancer cells and blood endothelial cells." (PMID 29593542, 2018). "The levels of MMP-1 in tumor samples of node positive patients were significantly higher than in samples of node negative patients and are associated with the 1G/2G polymorphism of the promoter region of MMP-1 in breast cancer patients." (PMID 30065181, 2018). "Considering the possible involvement of MMP1 in therapy response among breast cancer patients, we decided to further studies the underlying mechanisms." (PMID 28334049, 2017). "To further verify the findings, we examined the association between MMP1 expression and AE-free survival and MR-free survival among breast cancer patients by using bc-GenExMiner 4.0." (PMID 28334049, 2017). "High MMP1 expression is associated with worse survival outcomes in breast cancer patients after systematic therapy." (PMID 28334049, 2017). "In breast cancer, some recent studies reported that MMP1 upregulation is associated with more aggressive phenotype of breast cancer." (PMID 28334049, 2017). "MMP1 belongs to the metalloproteinase family and has been implicated in the progression and metastasis of breast cancer." (PMID 28885545, 2017). "Our results revealed a significant association of 2G/2G genotype of MMP1-1607 with steroid hormonal receptor status and metastasis, suggesting the importance of 2G/2G genotype in the progression of breast cancer." (PMID 28961241, 2017). "For example, the expression of MMP9, MMP13 and MMP14 all correlated with poor survival in patients with breast cancer, and expression of MMP1 and MMP2 was associated with highly aggressive breast cancer that metastasizes rapidly to the lung." (PMID 26956475, 2016). "Another promising candidate gene for breast cancer aggressiveness is MMP1, which belongs to a matrix metalloproteinase family associated with cell growth, metastasis, and the progression of different neoplasias, including breast cancer." (PMID 25391423, 2015). "MMP1 is a marker for poor prognosis in oesophageal- and breast cancer and is expressed also in tumour associated stroma." (PMID 26513020, 2015). "High MMP1 expression in tumor is associated with tumor evolution, poor prognosis and shortened survival in different types of tumors including breast cancer." (PMID 24972610, 2014). "In this translational study, we showed association between CTC with EMT phenotype (CTC_EMT) and MMP1 expression in primary breast cancer." (PMID 24972610, 2014). "Recently, MMP-1 and other bone metastasis-associated genes were evaluated as predictive biomarkers associated with breast cancer bone metastasis, and was highly expressed in both primary and metastatic breast cancer." (PMID 23696795, 2013). "Among MMPs, MMP-1 was identified as one of a small set of causal genes overexpressed in highly bone-metastatic clones of the breast cancer cell line MDA-MB-231, that has a functional role in induction of osteoclastogenesis." (PMID 23696795, 2013). "Further, in glioblastoma, melanoma and breast cancer, higher incidence has been associated with a single nucleotide polymorphism in an Ets-binding site which increases MMP-1 expression." (PMID 25339983, 2013). "Our study shows that MMP-1 is highly expressed by the brain metastasis-derived variants of the human MDA-MB-231 breast cancer cell line; this supports findings reported by others." (PMID 23217186, 2012). "We further evaluated the association between MMP-1 expression and the different molecular breast cancer subtypes." (PMID 21835023, 2011).
breast carcinoma (continued). "Recent reports suggest that MMP-1 associates with a shortened relapse free survival and poor outcome in breast cancer." (PMID 21835023, 2011). "Ki-67 expression and high MMP-1 positivity in tumour cells (cut-off 70%) were significantly associated with poor breast cancer-specific survival." (PMID 21835023, 2011). "In a bone metastasis model of breast cancer, bone-metastatic variants of the MDA-MB-231 breast cancer cell line were found to overexpress two metalloproteinases, MMP1 and ADAMTS1." (PMID 20010942, 2010). "For MMP-1, -7, -9, -13 and -14 an association between their high expression and a shortened relapse free survival in breast cancer patients was found." (PMID 19531263, 2009). "As such, the reverse correlation of plasma MMP1 with breast cancer risk and prognosis is to be expected." (PMID 18366705, 2008). "Several MMPs have been implicated as having a role in breast cancer, including MMP-1, MMP-2, MMP-3, and MMP-9, among others." (PMID 17922906, 2007). "Among the several existing MMPs, MMP1 has been identified in EVs associated with breast cancer." (PMID 40214422, 2025). "In this study, we provide evidence for the first time that PRDX3 could regulate cellular signaling pathways associated with Matrix Metalloproteinase-1 (MMP-1) expression and activity in breast cancer progression." (PMID 38321552, 2024). "The hypomethylation of matrix metallopeptidase 1 (MMP1) may be the cause of tamoxifen resistance in breast cancer." (PMID 37298314, 2023). "High MMP1 expression associates with worse OS in breast cancer patients after systematic therapy." (PMID 35057823, 2022). "The results also suggested that high MMP1 expression is associated with significantly worse AE-free survival and MR-free survival no matter in all breast cancer patients or only in ER+ breast cancer patients." (PMID 28334049, 2017). "High matrix metalloproteinase 1 (MMP1) expression is associated with enhanced breast cancer growth and metastasis and also might predict poor prognosis." (PMID 28334049, 2017). "Furthermore, high levels of MMP-1 expression are associated with poor prognosis and increased risk of bone metastasis in breast cancer patients." (PMID 26215578, 2015). "MMP-1 is an interstitial collagenase that has been implicated in breast cancer progression." (PMID 26215578, 2015). "Moreover, it has been suggested that MMP-1 is associated with shortened relapse-free survival and poor outcome in breast cancer." (PMID 25527274, 2014). "MMP1 expression in breast cancer cells was associated with high tumor grade, and increased proliferation (high Ki67), while MMP1 expression in tumor associated stroma, besides high tumor grade and increased proliferation, correlated with invasive ductal histology." (PMID 24972610, 2014). "Defining metastatic potential based on lymph node involvement or distant metastasis at the time of diagnosis, they observed that the GG genotype of MMP1 (−1607) was associated with over a two-fold increased risk of breast cancer metastasis especially among those with more European background." (PMID 23696797, 2013). "Furthermore, some SNPs of MMP-1 have been demonstrated to be significantly associated with increased risk for the development of lung cancer, breast cancer and colorectal cancer." (PMID 22655095, 2012). "Furthermore, some studies revealed that the MMP-1 promoter polymorphism (−1607 1G/2G) has an association with prognosis in tongue cancer, breast cancer and colorectal cancer." (PMID 22655095, 2012). "Also the positive correlation between HER2 and MMP-1 expression both in tumour cells and stromal cells in our study shows that MMP-1 is associated with poor outcome in breast cancer." (PMID 21835023, 2011).
breast carcinoma (continued). "Upregulation of MMP-1 was recently indicated to associate with poor outcome in breast cancer." (PMID 21835023, 2011). "MMP-1, -2, -8, -9, -10, -11, -12, -13, -15, -19, -23, -24, -27 and -28 might thus be associated with breast cancer development and tumor progression." (PMID 19531263, 2009). "In MCF-7 breast cancer cells, MMP1 is activated by Slug and enhances multidrug resistance; knockdown of Slug reduced MMP1 expression in these cells, further enhancing adriamycin resistance; in immune analysis, in luminal breast cancer, MMP1 is negatively associated with tumor survival." (PMID 35037689, 2022). "Third, the overexpression of MMP1 was associated with unfavorable survival results including overall survival (HR = 1.6; p = 1.6e-05), relapse free survival (HR = 1.78; p < 1e-16) and distant metastasis free survival (HR = 1.65; p = 5.3e-05) in patients with breast cancer." (PMID 29207651, 2017). "In addition, MMP-1 has been associated with multi-drug resistance in experimental breast cancer." (PMID 29387062, 2017). "The degradation of type I collagen by MMP-1 and -9 has been associated with rapid progression, poor overall survival and secondary metastasis, and it appears this process may have a pivotal role in the acquisition of invasive characteristics in breast cancer." (PMID 25013462, 2014). "Similarly, the converse of the haplotype MMP1 TCTC was inversely associated with breast cancer risk when looking at copy number for all women (OR 0.65, 95% CI 0.45,0.95 p = 0.027) and among women with the least Native American ancestry specifically (OR 0.60, 95% CI 0.40,0.91 p = 0.015)." (PMID 23696797, 2013). "MMP1 may prove be a breast cancer risk marker since it has been found in tissues with atypical ductal hyperplasia and in ductal lavage cells from patients at risk for developing breast cancer." (PMID 22276018, 2009). "Among those 11 protein candidates, we found 6 proteins that are involved in the progression and development of breast cancer, those are MMP-1, MMP-2, MMP-9, MMP-12, M-phase inducer phosphatase-2 (CDC25B), and Aldose reductase." (PMID 40176865, 2025). "Together, these findings indicate that MMP1 contributes to breast cancer cell survival via chemoresistance while contributing to breast cancer cell progression via the promotion of invasion and metastasis." (PMID 40214422, 2025). "Increased expression of matrix metalloproteinase-1 (MMP1), a member of the MMP family, is associated with poor survival outcomes, including disease progression and metastasis, in breast cancer." (PMID 41590789, 2025). "Transcriptomic analysis revealed upregulation of macrophage activation markers, genes such as S100A8, S100A2, KRT81, KRT6C, MARCO and MMP1, as well as processes related to keratinization and the formation of a cornified envelope in breast cancer cells." (PMID 41073799, 2025). "Several studies have shown that MMP-1 can promotes cell proliferation of breast cancer and plays a role in angiogenesis and metastasis, which can further progress breast cancer." (PMID 40176865, 2025). "We further investigated the role of MMP1 in breast cancer cell brain metastasis using in vivo experiments." (PMID 40885703, 2025). "As a crucial effector molecule in tumor progression, MMP1 shows significant correlation with breast cancer aggressiveness when highly expressed, and exhibits the highest gene score during brain metastasis dissemination." (PMID 40885703, 2025).